ANXA11 (annexin A11)
Diseases named in the same sentence as ANXA11 in open-access papers (continued):
Sharing a sentence is not in itself a finding about the gene and the disease.
metastatic colorectal cancer (2 papers, 2021 to 2022). "ANXA11 has also been associated with chemotherapy response in metastatic colorectal cancer, and ANXA11 nsSNP rs1049550 has been proposed as a biomarker to predict bevacizumab sensitivity in these patients." (PMID 36247003, 2022). "Strikingly, a single nucleotide polymorphism (SNP) in the Anxa11 gene, causing a mutation at position 230 (R230C), was associated with an increase in the overall response rate of metastatic colorectal cancer patients to bevacizumab, an angiogenesis inhibitor." (PMID 33810523, 2021). "The underlying mechanism remains to be clarified, but this Anxa11 SNP (rs1049550) may serve to improve the identification of metastatic colorectal cancer patients sensitive to bevacizumab regimens." (PMID 33810523, 2021).
motor neuron disease (2 papers, 2024 to 2026). "Here, we pathologically and biochemically analyzed four cases of primary lateral sclerosis-phenotype FTLD/motor neuron disease (MND) with TDP-43 pathology (PLS-TDP), and found that ANXA11 co-localizes with FTLD-TDP Type A pathology in PLS-TDP." (PMID 41486180, 2026). "When present in motor neuron disease, TDP-43 inclusions were more common than annexin A11 inclusions." (PMID 38896345, 2024).
muscular dystrophy (2 papers, 2023). Muscular dystrophy (MD) refers to a group of more than 30 genetic diseases characterized by progressive weakness and degeneration of the skeletal muscles that control movement. "The study of the new ANXA11 variant p.Asp40Ile in a patient with a unique childhood‐onset muscular dystrophy phenotype has demonstrated that disorders associated with ANXA11 Asp40 allelic variants have a common pathophysiology." (PMID 36651622, 2023). "Co-immunoprecipitation has revealed that annexin-A1 associates with dysferlin in a calcium- and membrane-injury-dependent manner, a behavior consistent with reported involvement of multiple annexins in muscle repair and muscular dystrophy (e.g., annexin A11)." (PMID 36902136, 2023).
oculopharyngeal muscular dystrophy (2 papers, 2023 to 2025). Oculopharyngeal muscular dystrophy (OPMD) is an adult-onset progressive myopathy characterized by progressive eyelid ptosis, dysphagia, dysarthria and proximal limb weakness. "Clinically, this study shows that pathologic changes in ANXA11 can cause a phenotype reminiscent of oculopharyngeal muscular dystrophy but with a strikingly earlier age of onset and a faster progression." (PMID 36651622, 2023). "Here we describe an individual with severe and rapidly progressive childhood‐onset oculopharyngeal muscular dystrophy who carries a new ANXA11 variant at position Asp40 (p.Asp40Ile; c.118_119delGAinsAT)." (PMID 36651622, 2023). "Taking into account the clinical similarities between our patient and HNRNPA2B1‐associated oculopharyngeal muscular dystrophy, we colabeled control and patient muscles using α‐ANXA11 and α‐hnRNPA2B1." (PMID 36651622, 2023). "Here we present a subject with a severe and rapidly progressive childhood‐onset oculopharyngeal muscular dystrophy who carries the new ANXA11 variant p.Asp40Ile, which increases ANXA11 aggregation in vitro and muscle fibers, and causes defects of SGs dynamics in fibroblasts." (PMID 36651622, 2023).
pulmonary fibrosis (2 papers, 2019 to 2024). Chronic progressive interstitial lung disorder characterized by the replacement of the lung tissue by connective tissue, leading to progressive dyspnea, respiratory failure, or right heart failure. "It has been proposed that alteration of ANXA11 is associated with pulmonary fibrosis in sarcoidosis." (PMID 31863066, 2019).
acute leukemia (1 paper, 2022). A clonal (malignant) hematopoietic disorder with an acute onset, affecting the bone marrow and the peripheral blood. "Further analysis using clinical datasets demonstrated that the elevated expression of a three-gene signature, consisting of SDHA, IDH3A, and ANXA11, was significantly associated with poor survival of acute leukemia patients." (PMID 35463978, 2022).
apraxia (1 paper, 2025). Apraxia is a neurological disorder characterized by the inability to perform tasks or movements, despite having the desire and physical ability to perform them. "In SQSTM1, VCP, and ANXA11 mutations, language impairment appears more variable, with some patients exhibiting speech apraxia or grammatical issues." (PMID 40649976, 2025).
bladder tumors (1 paper, 2021). "ANXA2, ANXA3, ANXA4, ANXA8, and ANXA9 were significantly increased in bladder tumor tissues, while ANXA6, ANXA7, and ANXA11 were significantly decreased." (PMID 34484309, 2021).
cholangiocarcinoma (1 paper, 2020). A carcinoma that arises from the intrahepatic biliary tree (intrahepatic cholangiocarcinoma) or from the junction, or adjacent to the junction, of the right and left hepatic ducts (hilar cholangiocarcinoma). "We selected 5 markers: CD44 and GPC4 were enriched in EVs from PDAC and cholangiocarcinoma organoids, while VGLUT2, CD14, and annexin A11 were enriched in EVs from PDAC organoids but not cholangiocarcinoma organoids." (PMID 32990680, 2020).
chronic pancreatitis (1 paper, 2020). A chronic inflammatory process causing damage and fibrosis of the pancreatic parenchyma. "To challenge the potential of EV markers CD14, GPC4, ANXA11, and CD44v6 in detecting PDAC patients, we analyzed their levels in a larger cohort of patients with PDAC and underlying pancreatic diseases: chronic pancreatitis and intraductal papillary mucinous neoplasm (IPMN)." (PMID 32990680, 2020).
corticobasal degeneration (1 paper, 2025). "Interestingly, an ANXA11 variant (P93S) has recently also been linked with corticobasal degeneration, and expression of this pathogenic ANXA11 variant reportedly induced TDP-43 mislocalization and dysfunction in cultured iPSC-derived neurons." (PMID 40468389, 2025).
diabetic nephropathy (1 paper, 2023). "Pathogenic conditions associated with aberrant expression of KDM6A, ANXA11 and SH3YL1 include pediatric cancer, ALS and diabetic nephropathy, respectively." (PMID 37026480, 2023).
glioblastoma (1 paper, 2022). The most malignant astrocytic tumor (WHO grade IV). "Finally, the present study allowed us to identify prognostic proteins for glioblastoma: PPP1R12A and RPS14 are favorable prognostic markers while ALCAM, ANXA11, and AltProt IP_652563 are unfavorable prognostic markers." (PMID 36333286, 2022).
glioma (1 paper, 2020). A benign or malignant brain and spinal cord tumor that arises from glial cells (astrocytes, oligodendrocytes, ependymal cells). "In this study, we firstly detected the correlation between miR-1343-3p and ANXA11 in glioma and analyzed their association with lncRNA EIF3J-AS1." (PMID 32905397, 2020). "In short, our study put forward a novel ceRNA pathway EIF3J-AS1/miR-1343-3p/ANXA11 in glioma and detected the functions of them in glioma growth." (PMID 32905397, 2020). "To further testify the ceRNA network of EIF3J-AS1/miR-1343-3p/ANXA11 in glioma, we overexpressed ANXA11 to evaluate the biological behaviors induced by EIF3J-AS1 silencing." (PMID 32905397, 2020). "All our findings indicated that EIF3J-AS1, miR-1343-3p and ANXA11 constituted a novel ceRNA pathway, which was responsible for the glioma growth." (PMID 32905397, 2020). "Collectively, this study was aimed at investigating the role of EIF3J-AS1/miR-1343-3p/ANXA11 axis in glioma growth." (PMID 32905397, 2020). "MiR-1343-3p inhibitor and ANXA11 overexpression offset the inhibitory impacts of EIF3J-AS1 silencing on glioma development." (PMID 32905397, 2020). "EIF3J-AS1/miR-1343-3p/ANXA11 axis significantly affected biological behaviors in glioma, suggesting new therapeutic target for glioma treatment." (PMID 32905397, 2020). "Hence, we concluded that EIF3J-AS1 promoted proliferation, while inhibiting apoptosis of glioma cells via positively regulating ANXA11 through sponging miR-1343-3p." (PMID 32905397, 2020). "Meantime, the apoptosis activity of glioma cells was facilitated by silencing ANXA11." (PMID 32905397, 2020). "The results showed that ANXA11 exhibited relative high level in glioma samples and cell lines." (PMID 32905397, 2020). "We knock out ANXA11 by transfecting sh-ANXA11 into glioma cells." (PMID 32905397, 2020). "We then detected the expression of ANXA11 in glioma samples and cell lines." (PMID 32905397, 2020). "ANXA11 silence significantly impaired the proliferative ability of glioma cells." (PMID 32905397, 2020). "Here, ANXA11 was proven to be the target mRNA of miR-1343-3p in glioma." (PMID 32905397, 2020). "However, the molecular relationship between EIF3J-AS1 and ANXA11 remains elusive in glioma." (PMID 32905397, 2020). "Importantly, ANXA11 silence led to the suppression of glioma cell growth." (PMID 32905397, 2020). "Mechanistically, EIF3J-AS1 relieved ANXA11 from miR-1343-3p silencing in the EIF3J-AS1/miR-1343-3p/ANXA11 RNA induced silencing complex (RISC), thus eliciting promoting effects on glioma progression." (PMID 32905397, 2020).
liver cancer (1 paper, 2021). An epithelial or non-epithelial malignant neoplasm that arises from the liver. "For instance, lncRNA AGAP2-AS1, as a ceRNA, exerts a pro-cancer effect in liver cancer by up-regulating ANXA11 expression via sponging miR-16-5p." (PMID 34037089, 2021).
Löfgren’s syndrome (1 paper, 2022). "We performed a case–control association study to investigate if ANXA11 associates with benign (Löfgren’s syndrome (LS)) or chronic sarcoidosis and performed a meta-analysis on previously reported findings." (PMID 35563867, 2022).
metastatic diseases (1 paper, 2025). "On the other hand, we suggest that drug combinations targeting ANXA3/ANXA6, and ANXA11/ANXA7 might be useful against lung- and liver-metastatic diseases, respectively." (PMID 40410902, 2025).
osteosarcoma (1 paper, 2023). A usually aggressive malignant bone-forming mesenchymal neoplasm, predominantly affecting adolescents and young adults. "In a proteomic screen, AnxA7 and Anx11 have been detected in mRNP complexes from human embryonic kidney cells, and AnxA11 is a component of mRNP complexes from U2OS bone osteosarcoma cells." (PMID 37397259, 2023).
pancreatic diseases (1 paper, 2020). "We detected clear signals for ANXA11 in PDAC patient EVs but rarely in EVs from patients with benign pancreatic diseases." (PMID 32990680, 2020).
cancer (15 papers, 2012 to 2024). A tumor composed of atypical neoplastic, often pleomorphic cells that invade other tissues. "Although confirmation from in vivo studies in mouse models are still limited, in certain cancers AnxA11 up- or downregulation appears to be linked to disease progression and development of drug resistance." (PMID 33810523, 2021). "Mutations and deregulation of ANXA11 are related to the development, chemoresistance, and recurrence of cancers, as well as are found in sarcoidosis and systemic autoimmune diseases." (PMID 32824294, 2020). "Aberrant ANXA11 functions are involved in drug resistance and recurrence of systemic autoimmune disease and cancer." (PMID 35463978, 2022). "Regarding human cancers, ANXA11 has been related to drug resistance and metastasis in several human malignancies." (PMID 36247003, 2022). "Anxa11 dysregulation is involved in the progression, drug-resistance, recurrence of systemic autoimmune disease and cancer." (PMID 26908448, 2016). "Species and/or cancer-subtype specific differences may exist, as ANXA11 downregulation in the murine Hca-P hepatocarcinoma cell line promoted in vivo tumour growth, lymph node metastatic potential and chemoresistance towards 5-fluorouracil." (PMID 33810523, 2021). "ANXA11 has been found to play a part in the biology of some cancers." (PMID 32905397, 2020). "Interestingly, prior global proteomic mapping of RNA binding proteins in cancer cells identified ANXA11 as an RNA binding protein." (PMID 31539493, 2019). "In addition to the described genes, we can individually identify WHSC1, PRDM14 and ANXA11 genes which are involved in autoimmune disorders and in some cancers." (PMID 30075788, 2018). "Dysregulation of Annexin A11 has been found in cancer, cancer treatment, and diabetes." (PMID 27071553, 2016). "Malignant tumors are characterized by high expression levels of S100A6 and ANXA11, suggesting that these proteins are related to cancer biology and regulation of the cell cycle." (PMID 32824294, 2020). "StarBase bioinformatics website screened out ANXA11 as the most potential combinable mRNA for miR-1343-3p (CLIP-Data ≥ 1, Degradome-Data ≥ 3, Pan-Cancer ≥ 8, programNum ≥ 1)." (PMID 32905397, 2020). "Consequently, by affecting the ANXA11 promoter, LINC00857 promotes the activation of the HSF1/LINC00857/ANXA11 signalling axis, which enhances the proliferation and spread of cancer cells." (PMID 39690143, 2024).
tumor (12 papers, 2008 to 2025). "High expression of ANXA11 was closely associated with adverse clinicopathological features, including larger tumor size, deeper invasion, lymph node metastasis, advanced TNM stage, and vascular invasion, suggesting a role in GC progression." (PMID 41244835, 2025). "ANXA11 is overexpressed in colon primary tumors compared to normal colon, and associated with tumor stage." (PMID 36247003, 2022). "In a mouse model for human hepatocellular carcinoma, ANXA11 upregulation was associated with increased Akt activation and contributed to tumour growth and progression." (PMID 33810523, 2021). "For instance, in ovarian cancer AnxA11 downregulation correlated with tumour recurrence and was associated with cisplatin resistance." (PMID 33810523, 2021). "Downregulated ANXA11 expression is associated with cisplatin resistance in ovarian cancer, and pointed as a useful biomarker to predict chemoresistance to platinum-based therapies and early tumor recurrence." (PMID 36247003, 2022). "In a recent study involving 63 paired GC and adjacent normal tissue samples, ANXA11 was found to be significantly upregulated at both the mRNA and protein levels in tumor tissues." (PMID 41244835, 2025). "The exceptions are ANXA5, ANXA6, ANXA10 and ANXA11, which play roles in several tumour types, while other ANXA members promote tumour cell proliferation." (PMID 36936694, 2023). "Immunohistochemistry assays displayed a dramatic reduction in the degree of Ki67 among ANXA11-silenced tumor tissues." (PMID 36010849, 2022). "ANXA11 acts as a tumor-suppressor in hepatocarcinoma regulating apoptosis, invasion and lymph node metastases." (PMID 36247003, 2022). "Conversely, the expression levels of ANXA6, ANXA7, and ANXA11 were significantly reduced in tumor tissues." (PMID 34484309, 2021). "Consistently, ANXA11 downregulation promoted the in vivo tumor growth and LNM capacities of Hca-P cells." (PMID 26908448, 2016). "The stable knockdown of ANXA11 enhances the in vitro migration and invasion capacities, in situ LN adhesion potential, in vivo tumor malignancy and LNM, and chemoresistance to 5-FU of Hca-P cells." (PMID 26908448, 2016). "Importantly, elevated ANXA11 expression was also confirmed in GC tissue samples, suggesting concordance between urinary excretion and tumor expression." (PMID 41244835, 2025). "This leads to the upregulation of ANXA11, which enhances tumor progression." (PMID 40739089, 2025). "The increase of tumor volumes showed statistical significances with P<0.05 in 11 and 15 days, and P<0.01 in 18 and 21 days for shAnxa11-Hca-P-transplanted mice compared with scramble-Hca-P-transplanted mice due to Anxa11 downregulation." (PMID 26908448, 2016). "ANXA11 downregulation inversely correlated in vivo tumor formation of Hca-P cells." (PMID 26908448, 2016). "However, for annexin A11, moderate staining was observed in 33.3% of tumours compared to 31.1% of tumours that showed strong staining." (PMID 18071363, 2008). "Lastly, ANXA11 was evaluated only in tumor tissues, without examining its expression or utility as a non-invasive biomarker in serum or urine, limiting its clinical applicability in early detection or monitoring." (PMID 41244835, 2025). "Additionally, although the study demonstrated significant functional roles of ANXA11 in vitro, it lacked in vivo validation using animal models to confirm its effects on tumor growth and metastasis." (PMID 41244835, 2025). "However, in our report, we demonstrated that the expression of ANXA9 and ANXA11 in KIRC tissues was lower than that in normal tissues, and the expression did not correlate with tumour stage." (PMID 39290334, 2022).
neurodegenerative disease (6 papers, 2019 to 2024). A disorder of the central nervous system characterized by gradual and progressive loss of neural tissue and neurologic function. "We further identified additional patients with mutations in ANXA11 and similar clinical presentations from a large neurodegenerative disease cohort, thereby establishing CBS as part of the phenotypic spectrum of ANXA11 mutations." (PMID 38923692, 2024). "We then extended our immunohistochemistry study to screen a wide variety of sporadic and genetic forms of ALS, FTLD–TDP, LATE-NC and other neurodegenerative disease cases for annexin A11 aggregates." (PMID 38896345, 2024).
neurological disease (4 papers, 2023 to 2024). "Further studies are required to better understand the pathophysiologic mechanisms by which TDP-43 and annexin A11 aggregation leads to neurologic disease." (PMID 38896345, 2024). "Besides, several genes appear to be associated with other neurological disorders, such as CCNF and ANXA11 linked to FTD." (PMID 37250416, 2023).
myopathies (1 paper, 2023). "The phenotypic spectrum of ANXA11 mutations has recently expanded into myopathies, with the description of Brazilian and Greek families that carry the N‐terminal variant p.Asp40Tyr." (PMID 36651622, 2023). "Some ALS‐related variants are known to affect ANXA11 IDD; however, the mechanism by which the myopathy occurs is unknown." (PMID 36651622, 2023).
ANXA11 also shares sentences with these, for which no sentence is quoted: breast carcinoma (3 papers); gastric cancer (3); progressive supranuclear palsy (2); Anxiety (1); autoimmune disorders (1); autoimmune pancreatitis (1); behavioral variant frontotemporal dementia (1); cardiac sarcoidosis (1); celiac disease (1); clear cell renal carcinoma (1); dementia (1); gastric tumors (1); IgG4-related disease (1); juvenile idiopathic arthritis (1); leukemia (1); memory impairment (1); nephropathies (1); nephrotic syndrome (1); ovarian serous tumor (1); pancreatic cancer (1); pediatric cancer (1); preeclampsia (1); primary biliary cirrhosis (1); Primary lateral sclerosis (1); primary progressive aphasia (1); pulmonary sarcoidosis (1); semantic dementia (1); systemic immune disorder (1); tauopathy (1); type 1 diabetes (1).